POTEF (POTE ankyrin domain family member F)
Synonyms: A26C1B; POTEACTIN; POTE2alpha
Tractability: PROTAC: ubiquitination databases record sites on it.
Gene: Protein-coding gene on chromosome 2 (130,073,535 to 130,129,222, reverse strand). Ensembl gene ENSG00000196604.
Subcellular location: Cytoplasm, cell cortex
Gene Ontology:
Molecular function: protein binding; protein kinase binding; structural constituent of postsynaptic actin cytoskeleton
Biological process: axonogenesis; cell motility; postsynaptic actin cytoskeleton organization
Cellular component: blood microparticle; extracellular exosome; extracellular region; actin cytoskeleton; actin filament; axon; cytoplasm; membrane; NuA4 histone acetyltransferase complex; synapse; cell cortex
Genetic constraint (gnomAD): Loss-of-function variants: 18 observed, 42.39 expected, observed/expected ratio (o/e) 0.42, 90% interval 0.29 to 0.63. The synonymous counts are far from expectation, so gnomAD's model fits this gene poorly and the ratio says little. Missense variants: 507 observed, 681.5 expected, observed/expected ratio (o/e) 0.74, 90% interval 0.69 to 0.8. Synonymous variants: 177 observed, 230.1 expected, observed/expected ratio (o/e) 0.77, 90% interval 0.68 to 0.87.
Homologues: Paralogues in human: POTEE (99% identical), POTEI (97% identical), POTEJ (93% identical), POTEB3 (47% identical), POTED (46% identical), POTEB (44% identical), POTEB2 (44% identical), POTEC (44% identical), POTEG (43% identical), POTEH (43% identical), POTEM (43% identical), POTEA (35% identical), and 2 more.
Diseases named in the same sentence as POTEF in open-access papers:
POTEF is named in the same sentence as 9 diseases in open-access papers, as found by Europe PMC text mining. Sharing a sentence is not in itself a finding about the gene and the disease. The quoted sentences say what the papers report.
anaphylaxis (1 paper, 2025). An acute hypersensitivity reaction that occurs from exposure to an allergen. "However, based on their known biological roles—POTEF in retinal homeostasis, MUC4 in mucin production, and SPATA31A1 in cell differentiation and spermatogenesis —it is unlikely that these genes are directly involved in the pathogenesis of cefaclor‐induced anaphylaxis." (PMID 40974473, 2025).
pancreatic cancer (1 paper, 2024). "In this study, we found a significant association between pancreatic cancer driver genes, EGF, EPHB3, and POTEF, and original.glrlm.RunVariance." (PMID 38811597, 2024).
pneumonia (1 paper, 2024). An acute, acute and chronic, or chronic inflammation focally or diffusely affecting the lung parenchyma, caused by an infection in one or both of the lungs (by bacteria, viruses, fungi, or mycoplasma.). "However, the role of POTEF in pneumonia caused by Omicron is not clear, and our findings suggest that POTEF is involved in tissue coagulation processes, participating in disease inflammation and cell regulatory responses." (PMID 38424541, 2024).
prostate carcinoma (1 paper, 2019). A carcinoma that arises from epithelial cells of the prostate gland. "Furthermore, recent findings indicated the roles of POTEF, one of homologous protein of POTEE, in the regulation of apoptosis in prostate cancer cells." (PMID 31723122, 2019).
triple-negative breast carcinoma (1 paper, 2020). An invasive breast carcinoma which is negative for expression of estrogen receptor (ER), progesterone receptor (PR), and human epidermal growth factor receptor 2 (HER2). "Ricinus communis agglutinin I (RCA-I), which specifically interacts with terminal galactose moieties, binds the membrane glycoprotein POTE ankyrin domain family member F (POTEF) in triple-negative breast cancer (TNBC) cells proportionally to their metastatic abilities." (PMID 32509848, 2020).
cancer (1 paper, 2024). A tumor composed of atypical neoplastic, often pleomorphic cells that invade other tissues. "The association between these three genes, EGF, EPHB3, and POTEF, and Run Variance indicates their roles in the heterogeneous colonization of cancer cells." (PMID 38811597, 2024).
tumor (1 paper, 2017). "The most up regulated protein identified in HEY Oct4A KD xenograft tumor samples was the apoptosis-associated protein POTEF (Rsc 23.0)." (PMID 28406185, 2017). "However, proteins which appear to be involved in cellular apoptosis (e.g. POTEF) and tumor suppression (APOA1) were also noted to be up regulated following Oct4A suppression." (PMID 28406185, 2017).
POTEF also shares sentences with these, for which no sentence is quoted: hearing loss (1 paper); psoriasis (1).